TLR7 (toll like receptor 7)
Diseases named in the same sentence as TLR7 in open-access papers (continued):
Sharing a sentence is not in itself a finding about the gene and the disease.
viral infection (continued). "Although the detailed mechanism of these TLR7 SNPs on different viral diseases is not clear, combined with SNP functions found in previous studies, these two TLR7 intronic SNPs may play critical roles in various viral diseases and play different roles in acute/chronic disease phases." (PMID 33193416, 2020). "Although such a negative regulation of IFN-γ by type I IFN has been observed during viral infection in an IFNAR- and STAT1-dependent manner, this has never been described in the context of TLR7/8-adjuvanted vaccines." (PMID 33262759, 2020). "Correspondingly, phosphorylation of NF-κB p65 and IκBα was enhanced in cells containing TLR7 upon EV71-infection, but not in mock-infected cells, indicating that TLR7 activates NF-κB during viral infection." (PMID 28854257, 2017). "pDCs release large quantities of IFN during viral infection, and here we show that splenic pDCs exposed to RV in vitro display impaired release of IFN-α and IFN-β but not λ2/3 in the absence of TLR7." (PMID 26108570, 2015). "In a number of viral infection models, IFN-α and -β production by pDCs was mediated by TLR7/9 and was at least partially independent of a positive IFN-αβ feedback." (PMID 19008951, 2008).
COVID-19 (230 papers, 2020 to 2026). A disease caused by infection with severe acute respiratory syndrome coronavirus 2. "Inborn errors of type I interferon immunity (IFN-I-IEIs), including X-linked TLR7 deficiency, account for ~ 2% of critical COVID-19 cases." (PMID 41578410, 2026). "Low TLR7 levels were associated with severe COVID-19, and together with OAS1 expression were modulated over time according to severity." (PMID 41445728, 2025). "The comprehensive study of genetic susceptibility to COVID-19 has provided substantial evidence that rare TLR7 variants are associated with an increased risk of developing severe forms of the disease." (PMID 40423910, 2025). "In our analysis, lower TLR7 expression was independently associated with both lymphopenia and severe COVID-19, supporting the link between these observations." (PMID 41445728, 2025). "This study investigates the association between TLR7 variants and susceptibility to severe COVID-19 in a multicentric Spanish cohort." (PMID 40423910, 2025). "Despite the small sample size, our study identified the C allele of the rs3853839 SNP in TLR7 as dominant in the TNFHIFNγH group; in this sense, recently, it has been proposed that rs3853839 presence increases the risk of severe outcomes of COVID-19." (PMID 39940907, 2025). "The TLR7 rs179008 T allele is a potential genetic risk factor for severe post-COVID-19 inflammatory syndromes in boys, likely due to impaired immune signaling." (PMID 40943412, 2025). "Studies in males with deleterious TLR7 variants support this sex-based vulnerability to COVID-19, suggesting that the TLR7 gene-dose effect renders males more susceptible to severe outcomes." (PMID 40943412, 2025). "In women, biallelic expression has been linked to enhance TLR7-dependent immune response, potentially explaining the protective effect of female sex against severe COVID-19." (PMID 40423910, 2025). "Our group reported a rare TLR7 N215S variant in two healthy brothers who experienced severe COVID-19." (PMID 40423910, 2025). "In this context, our study aims to evaluate the contribution of rare and common TLR7 variants to COVID-19 severity in a multicenter Spanish cohort, including the functional analysis of selected rare variants." (PMID 40423910, 2025). "Some reports have revealed an association of rare TLR7 gene variants with COVID-19, specifically in young male patients who required supplemental oxygen, suggesting the involvement of these TLR7 variants in the severity of the disease." (PMID 39940907, 2025). "Loss-of-function TLR7 variants or X-linked TLR7 mutations/deficiencies are associated with severe COVID-19 (53, 77, –, 83)." (PMID 40162785, 2025). "Several elegant human studies have also demonstrated that inborn errors in IFNs, autoantibodies against IFNs, and mutations/deficiencies in TLR3 and TLR7 signaling are associated with severe COVID-19 (53, –, 73)." (PMID 40162785, 2025). "pDCs and other myeloid or myeloid-derived cells isolated from TLR7-deficient COVID-19 patients presented a defective IFN/ISG response." (PMID 40162785, 2025). "Here we present the results of an in-depth analysis of TLR7 variants identified in a Spanish multicenter cohort of COVID-19 patients, finding rare TLR7 variants in 3.96% unvaccinated hospitalized cases, while no rare variants were detected in controls." (PMID 40423910, 2025). "Studies that identified TLR7 deficiency as a monogenic form of severe COVID-19 were limited to the TLR7 coding region, and thus did not consider potential causal variants in adjacent regions with evidence of regulatory function (including structural variants)." (PMID 39715278, 2024). "IMQ does not stimulate the innate immune system of people who present these unfunctional TLR7 variants; therefore, young individuals with TLR7 mutants develop severe COVID-19, suggesting that TLR7 and TLR8 are important in SARS-CoV-2 protection." (PMID 39062904, 2024).
COVID-19 (continued). "Later studies have additionally revealed novel, rare XL LOF variants in TLR7 in young males critically ill with COVID-19, with these defects being shown to underlie severe COVID-19 disease in 1–2% of men under 60 years of age." (PMID 38932404, 2024). "Severe and fatal COVID-19 is associated with a lower expression of TLR7 and TLR8 compared to that in survivors." (PMID 39062904, 2024). "X-linked recessive TLR7 deficiency leads to about 1.8% of men under 60 years old suffering from life-threatening COVID-19 due to impaired type I IFNs in response to SARS-CoV-2." (PMID 39339845, 2024). "Specifically, X-linked LoF variants in TLR7, encoding a receptor for single-stranded RNA highly expressed in plasmacytoid dendritic cells (pDCs), have been estimated to cause 1% of critical COVID-19 cases in males under 60 years old." (PMID 38231281, 2024). "Deficiency of TLR7 functional activity is associated with a strong predisposition to severe COVID-19 in men." (PMID 39457048, 2024). "While we did not detect any causal variant in or around the established risk gene TLR7, the analyses identified carrier status for six autosomal-recessive monogenic disorders in young males who had been hospitalized due to COVID-19." (PMID 39715278, 2024). "The TLR7 rs3853839 (G/C) variation was found to be associated with the severity of coronavirus disease 2019 (COVID-19) and with the persistence of HCV infection." (PMID 39650644, 2024). "Along with this idea, severely affected male COVID-19 patients carrying loss-of-function TLR7 variants exhibit decreased levels of ACOD1 mRNA." (PMID 38605883, 2024). "We aimed to identify any link between TLR7 polymorphisms and their potential influence on COVID-19 susceptibility." (PMID 38066751, 2023). "To conclude, TLR7 LOF mutations increase the risk of critical COVID-19 due to loss of viral RNA sensing ability and disrupted MyD88 signaling." (PMID 37567916, 2023). "It would be interesting if the severe COVID-19 outcome of TLR7-deficient human patients is due to an impaired anti-SARS-CoV-2 B cell response." (PMID 36648888, 2023). "TLR7 deficiency was found to account for 1% of cases of critical COVID-19 in men and about 1.8% of cases of critical COVID-19 in male patients below the age of 60 years." (PMID 37196358, 2023). "Rare autosomal inborn errors of type I IFN-dependent immunity to influenza viruses can underlie critical forms of COVID-19, especially in subjects below 60 years of age, in addition to X-linked TLR7 deficiency." (PMID 37020259, 2023). "In this way, dependence on functional TLR7-signaling for initial innate immune responses highlights the crucial role of the X-linked recessive TLR7 deficiency in the pathogenesis of COVID-19." (PMID 37175768, 2023). "The penetrance of TLR7 deficiency for severe or critical COVID-19 among relatives of index cases was high, but incomplete, especially in children." (PMID 37196358, 2023). "Given the role that TLR7 plays in COVID-19, genetic screening of TLR7 gene polymorphisms in COVID-19 patients must be investigated." (PMID 38066751, 2023). "They reported two families with affected males at a mean age of 26 years, with no history of major chronic disease, characterized by rare loss-of-function (LOF) TLR7 variants who suffered from severe COVID-19." (PMID 37175768, 2023). "Rare putative loss-of-function variants of the X-chromosome-located TLR7 gene are associated with altered type I IFN expression in young men with severe COVID-19." (PMID 36926280, 2023). "X-linked recessive TLR7 deficiency was found in about 1% to 2% of male patients with critical COVID-19." (PMID 36719370, 2023). "After the intersection with TLR7-related disease using Opentargets, we discovered that TLR7 was associated with COVID-19." (PMID 37362864, 2023). "In the current study, we aimed to search for genetic variations associated with COVID-19 patients in the coding region of TLR7 gene of a Korean female population." (PMID 38066751, 2023).
COVID-19 (continued). "Using amplicon sequencing, we screened the genetic polymorphisms in the coding region of the TLR7 gene in COVID-19 patients and healthy controls." (PMID 38066751, 2023). "Rare variants of TLR3- and TLR7-dependent type I IFN immunity genes can underlie life-threatening COVID-19, particularly with recessive inheritance, in patients under 60 years old." (PMID 37020259, 2023). "Surprisingly, genetic analysis of young brothers who developed severe COVID-19 identified for the first-time humans with TLR7-deficiency." (PMID 36648888, 2023). "The presence of these rare variants in young men with severe COVID-19 has been studied, resulting in TLR7 missense variants in 14.3% of the patients." (PMID 38066751, 2023). "While TLR7 expression has been implicated in respiratory syncytial virus-induced lung inflammation, several studies have reported associations between COVID-19 and TLR7 variants." (PMID 38066751, 2023). "In the current study, our aim was to search for genetic variations associated with COVID-19 patients in the TLR7 gene of a Korean population." (PMID 38066751, 2023). "The X chromosome androgen receptor AR that, like many EDS-contributing genes, impacts muscle (M313200+) and joins ACE2, TLR7, and six other X chromosome genes as potential factors in male susceptibility to COVID-19." (PMID 37504295, 2023). "In a case series of four young male patients, X-chromosomal loss-of-function variants of the gene encoding for Toll-like receptor 7 were associated with severe COVID-19." (PMID 34467455, 2022). "In contrast, the TLR7 mutation, which impairs the function of the protein, is most likely responsible for the severe COVID-19." (PMID 34686943, 2022). "It was observed that the toll-like receptor 7 (TLR7) gene is associated with poor prognosis among patients with COVID-19." (PMID 35409036, 2022). "In two unrelated young brother pairs with critical COVID-19, rare genetic variants in the X-chromosomal Toll-like receptor 7 (TLR7) were identified by rapid clinical whole-exome sequencing (WES)." (PMID 35986347, 2022). "Another study found that in men under 60 years recessive TLR7 deficiency accounts for 1% of critical COVID-19 cases." (PMID 36142877, 2022). "With ACAT, the association between TLR7 and severe COVID-19 (p = 1.58x10-6), and between MARK1 and hospitalisation (p = 4.30x10-7) remained exome-significant." (PMID 36327219, 2022). "On the one hand, there is robust evidence supporting that the presence of X-linked deleterious variants in the TLR7 gene are causal for life-threatening COVID-19 only affecting males." (PMID 35708486, 2022). "A first glimpse at severe COVID-19 pathogenesis arose with the identification by exome sequencing of hemizygous loss-of-function (LoF) mutations in the X-linked TLR7 gene in two pairs of young brothers who developed severe pneumonia." (PMID 35768520, 2022). "Further a meta-analysis of worldwide exome and genome data implicated rare disease-causing variants in TLR7 in exacerbating the COVID-19 clinical course." (PMID 36143338, 2022). "Another study identified two rare mutations in TLR7 in four young males with severe COVID-19 from two unrelated families." (PMID 35336937, 2022). "In summary, we reproduced an exome-wide significant association with severe COVID-19 outcomes in carriers of rare deleterious variants at TLR7, for both sexes." (PMID 36327219, 2022). "These preliminary findings describing X-linked TLR7 deficiency (OMIM #301051) in patients with critical COVID-19 have subsequently been replicated in several other cohorts." (PMID 35986347, 2022). "Due to loss-of-function mutations that suppress the antiviral response to SARS-CoV-2, TLR7 variants constitute a major risk factor for severe COVID-19 in men under the age of 50." (PMID 35847031, 2022). "The identification of male hemizygous TLR7 mutation carriers is particularly relevant given the high clinical penetrance for severe COVID-19, as only few asymptomatic carriers have been reported so far." (PMID 35986347, 2022).
COVID-19 (continued). "The burden of rare variants in TLR7 was found to be significantly higher in patients with severe COVID-19 in pan-ancestry WES data from the UK biobank." (PMID 36204639, 2022). "We nevertheless cannot exclude the possibility that the ATM deficiency modified the course of COVID-19 in our TLR7-deficient patient." (PMID 34686943, 2022). "An X-linked recessive TLR7 deficiency was found present in approximately 1% of men under 60 years old with life-threatening COVID-19)." (PMID 35956081, 2022). "Regarding TLRs, it has been shown that certain patients with severe COVID-19 were associated with a rare putative loss-of-function variants of X-chromosomal TLR7, that causes poor defense against coronavirus." (PMID 35956081, 2022). "Specifically, a TLR7 (rs179008) polymorphism has been associated with increased risk of pneumonia in patients with COVID-19, and deleterious TLR7 variants are associated with more severe disease." (PMID 36419185, 2022). "TLR7 participates in recognition of single-stranded RNA viruses, which this gene is associated with COVID-19." (PMID 36553678, 2022). "The most recent research from 21 cohorts across 12 countries also reported that rare, deleterious TLR7 variants are risk factors that predisposed the severity of COVID-19 (13.1-fold increase)." (PMID 36292769, 2022). "Hemizygous deleterious variants have also been identified in TLR7 in ~1% of males who developed severe/fatal COVID-19." (PMID 35748970, 2022). "A preliminary case study of young male patients with COVID-19 identified loss-of-function variants of TLR7 that were associated with severe clinical disease." (PMID 35246245, 2022). "In our study, we observed that individuals with rare deleterious variants at TLR7 are at increased risk of severe COVID-19 (up to 13.1-fold increase in odds in those with pLoFs)." (PMID 36327219, 2022). "TLR7 was one of the most important susceptibility genes found in an Italian cohort of COVID-19 patients, where 6.3% of young males with life-threatening disease presented missense variants of this gene." (PMID 35783606, 2022). "X-linked TLR7 deficiency is expected to account for approximately 1% of cases of severe or critical COVID-19 in men aged under 60 years of age, which is expected to be even higher with stricter screening criteria." (PMID 35986347, 2022). "The whole exome sequencing of four previously healthy men with severe COVID-19 also revealed the presence of putative loss-of-function variants in X-chromosomal TLR7." (PMID 35631059, 2022). "In this cohort of young males affected with severe COVID-19 rare TLR7 variants were prospectively identified in 2 out of 14 cases (14.3%)." (PMID 34367187, 2021). "Since the first report on TLR7 variants in severe COVID-19, diagnostic pipelines have been developed to discover such mutations." (PMID 33752797, 2021). "The studyidentified two different rare novel TLR7 loss-of-functionvariants.The analysis of men with severe COVID-19 aged less than 60 years foundTLR7 deleterious missense variants in 2.1% of the patientsand in none of the asymptomatic participants." (PMID 34436508, 2021). "Loss-of-function TLR7 variants have been recently reported in a small number of males to underlie strong predisposition to severe COVID-19." (PMID 34367187, 2021). "We therefore propose clinical screening criteria for the identification of TLR7 variants in male patients with severe COVID-19." (PMID 34367187, 2021). "Functional studies have started to shed light on the mechanism by which TLR7 variants can lead to severe COVID-19." (PMID 33752797, 2021). "Young males with TLR7 loss-of-function variants and severe COVID-19 represent a subset of male patients contributing to disease susceptibility in up to 2% of severe COVID-19." (PMID 33650967, 2021).